HINT1 (histidine triad nucleotide binding protein 1)
Description:
Exhibits adenosine 5'-monophosphoramidase activity, hydrolyzing purine nucleotide phosphoramidates with a single phosphate group such as adenosine 5'monophosphoramidate (AMP-NH2) to yield AMP and NH2. Hydrolyzes adenosine 5'monophosphomorpholidate (AMP-morpholidate) and guanosine 5'monophosphomorpholidate (GMP-morpholidate). Hydrolyzes lysyl-AMP (AMP-N-epsilon-(N-alpha-acetyl lysine methyl ester)) generated by lysine tRNA ligase, as well as Met-AMP, His-AMP and Asp-AMP, lysyl-GMP (GMP-N-epsilon-(N-alpha-acetyl lysine methyl ester)) and AMP-N-alanine methyl ester. Hydrolyzes 3-indolepropionic acyl-adenylate, tryptamine adenosine phosphoramidate monoester and other fluorogenic purine nucleoside tryptamine phosphoramidates in vitro. Can also convert adenosine 5'-O-phosphorothioate and guanosine 5'-O-phosphorothioate to the corresponding nucleoside 5'-O-phosphates with concomitant release of hydrogen sulfide. In addition, functions as scaffolding protein that modulates transcriptional activation by the LEF1/TCF1-CTNNB1 complex and by the complex formed with MITF and CTNNB1. Modulates proteasomal degradation of target proteins by the SCF (SKP2-CUL1-F-box protein) E3 ubiquitin-protein ligase complex. Also exhibits SUMO-specific isopeptidase activity, deconjugating SUMO1 from RGS17. Deconjugates SUMO1 from RANGAP1 (By similarity).
Synonyms: PKCI-1; HINT; PRKCNH1; NMAN
Tractability: Small molecule: a structure with a bound ligand is known; a high-quality ligand is known. Antibody: its Gene Ontology location is reachable by antibodies, with high confidence; the Human Protein Atlas places it where antibodies can reach. PROTAC: ubiquitination databases record sites on it; its protein half-life has been measured; a small molecule that binds it is known.
Target class: Enzyme; Hydrolase
Gene: Protein-coding gene on chromosome 5 (131,155,383 to 131,224,468, reverse strand). Ensembl gene ENSG00000169567.
Subcellular location: Cytoplasm; Nucleus
Subcellular location (Human Protein Atlas): Cytosol; Plasma membrane; Nucleoplasm
Pathways (Reactome):
Developmental Biology: Regulation of MITF-M-dependent genes involved in apoptosis; Regulation of MITF-M-dependent genes involved in cell cycle and proliferation; Transcriptional and post-translational regulation of MITF-M expression and activity
Gene Ontology:
Molecular function: adenosine 5'-monophosphoramidase activity; deSUMOylase activity; hydrolase activity; protein binding; protein kinase C binding; catalytic activity
Biological process: protein desumoylation; purine ribonucleotide catabolic process; regulation of DNA-templated transcription; signal transduction; positive regulation of calcium-mediated signaling
Cellular component: cytoplasm; cytosol; extracellular exosome; histone deacetylase complex; nucleoplasm; nucleus; cytoskeleton
Genetic constraint (gnomAD): Loss-of-function variants: 12 observed, 10.38 expected, observed/expected ratio (o/e) 1.16, 90% interval 0.74 to 1.78. The upper end of that interval is the gene's LOEUF score, 1.78, which puts it in group 6 of 6, group 1 being the genes least tolerant of losing a copy. Missense variants: 143 observed, 160.48 expected, observed/expected ratio (o/e) 0.89, 90% interval 0.78 to 1.02. Synonymous variants: 40 observed, 54.9 expected, observed/expected ratio (o/e) 0.73, 90% interval 0.56 to 0.95.
Gene-disease validity (ClinGen):
ClinGen rates the evidence that HINT1 causes each of these diseases.
Charcot-Marie-Tooth disease (autosomal recessive): Definitive. An inherited degenerative disorder involving the peripheral nerves.
Homologues: Orthologues: chimpanzee HINT1 (100% identical), macaque HINT1 (99% identical), rabbit HINT1 (96% identical), pig HINT1 (95% identical), mouse Hint1 (94% identical), rat Hint1 (94% identical), rat Hint1l2 (94% identical), rat Hint1l2 (87% identical), tropical clawed frog hint1 (78% identical), guinea pig HINT1 (68% identical), Caenorhabditis elegans hint-1 (63% identical). Paralogues in human: HINT2 (60% identical), FHIT (22% identical).
Diseases named in the same sentence as HINT1 in open-access papers:
HINT1 is named in the same sentence as 84 diseases in open-access papers, as found by Europe PMC text mining. Sharing a sentence is not in itself a finding about the gene and the disease. The quoted sentences say what the papers report.
schizophrenia (17 papers, 2009 to 2024). A major psychotic disorder characterized by abnormalities in the perception or expression of reality. "It is encoded by the HINT1 gene located on chromosome 5q31.22 in a region linked to schizophrenia in genetic studies." (PMID 38279213, 2024). "The histidine triad nucleotide-binding protein-1 gene is implicated in schizophrenia and the behavioural effects of morphine and amphetamine." (PMID 38279213, 2024). "The HINT1 and σ1R genes have also been implicated in schizophrenia, moreover the σ1R agonist pregnenolone and antagonists showed promising results in reducing the symptoms of schizophrenia in clinical trials." (PMID 28758944, 2017). "rs2551038 is located in an intron of the HINT1 gene and is associated with ND and schizophrenia." (PMID 39062900, 2024). "They further compared expression levels of HINT1 in postmortem brain samples provided by the Stanley Medical Research Institute and concluded that mutations in the HINT1 gene were potentially correlated with schizophrenia." (PMID 29214080, 2017). "The HINT1 gene is located on a genetic locus highly associated with schizophrenia (5q31.2)." (PMID 29214080, 2017). "Moreover, a possible gender-specific (male) association between HINT1 and schizophrenia has been hypothesized." (PMID 39596683, 2024). "Additionally, the intra-module hub gene from a yellow module with the highest value of connectivity was a schizophrenia-associated gene known as HINT1, and two of the top five connected intra-module hubs in module yellow were MRPS18C and NDUFA12, which are implicated in the function of mitochondria." (PMID 29958387, 2018). "Hence, the endocannabinoid system as a target of exocannabinoids is a candidate to produce schizophrenia by inducing NMDAR hypofunction and/or altering NMDAR-GPCR cross-regulation, while in humans the HINT1 and σ1R genes have also been implicated in schizophrenia." (PMID 27323834, 2016). "The analysed single-nucleotide polymorphism rs2526303 is located in the non-coding region of the HINT1 gene and has been investigated before in two studies regarding schizophrenia and nicotine dependence." (PMID 38279213, 2024). "Expression studies have found that HINT1 mRNA levels are significantly reduced in the prefrontal cortex (PFC) of males with schizophrenia compared to controls." (PMID 38279213, 2024). "Association and expression studies reveal the involvement of the HINT1 gene in schizophrenia and bipolar disorder." (PMID 39062900, 2024). "Expression studies have shown that the level of HINT1 mRNA is significantly reduced in the prefrontal cortex (PFc) of male patients with schizophrenia compared to control subjects." (PMID 37373392, 2023). "In fact, NR1 C1 subunits are enhanced in depressive patients and they diminish in those affected by schizophrenia, augmenting five-fold in σ1R−/− mice and about two-fold in HINT1−/− mice." (PMID 34827679, 2021). "These values, when normalized to HINT1 expression (F = 10.33, p < 0.0001), showed a pattern of enhanced expression in schizophrenia similar to that seen for MORs (LSD post-hoc test, p < 0.0001)." (PMID 29249810, 2017). "In this context, the interaction of GPCRs with NMDARs regulated by HINT1-σ1R deserves attention mostly because the main components of this switch have been described as vulnerability genes for schizophrenia [see 25, 67]." (PMID 26461475, 2015). "PKCI/HINT1 gene knockout (KO) mice display hyper-locomotion in response to D-amphetamine which is considered a positive symptom of schizophrenia in animal models." (PMID 19912621, 2009). "Postmortem studies identified PKCI/HINT1 as a candidate molecule for schizophrenia and bipolar disorder." (PMID 19912621, 2009). "The downregulation of HINT1 has also been reported in diabetes, AD, and schizophrenia." (PMID 35445545, 2022). "In addition, multiple candidate genes implicated in schizophrenia or other psychiatric disorders were detected, such as SST, NPY, SLC32A1, HINT1, RELN, and IFITM3." (PMID 29958387, 2018).
schizophrenia (continued). "The same team then evaluated eight single nucleotide polymorphisms (SNPs) in the HINT1 gene in Irish study of high-density schizophrenia families (ISHDSF, 1350 subjects and 273 pedigrees) and Irish case-control study of schizophrenia (ICCSS, 655 patients and 626 controls)." (PMID 29214080, 2017). "Considering that schizophrenia is often accompanied by dopaminergic system hyperfunction and the hyperactivity induced by AMPH represents the positive symptom-like behavior in rodent models for schizophrenia, HINT1 KO mice appear to be a useful genetic animal model for studying schizophrenia." (PMID 29214080, 2017). "Moreover, HINT1 is related to gender‐specific acute behavior changes in schizophrenia and in response to nicotine." (PMID 29075577, 2017). "Accumulating clinical and preclinical evidence suggests that HINT1 may play an important role as a neuroplastic mediator in neuropsychiatric diseases, such as schizophrenia, inherited peripheral neuropathies, mood disorders, and drug addiction." (PMID 29214080, 2017). "Notably, the HINT1 gene is located in the SPEC2/PDZ-GEF2/ACSL6 region of 5q22-23, which is associated with schizophrenia." (PMID 29214080, 2017). "Additionally, the correlations between schizophrenia and HINT1 are sex specific, and nicotine‐mediated acute behavior changes also show different effects in males and females." (PMID 29075577, 2017). "PKCI/HINT1 was identified as a candidate molecule in the neuropathology of schizophrenia when its gene expression was shown to be decreased via microarray analysis in the prefrontal cortex of schizophrenic patients, as subsequently validated by real-time quantitative polymerase chain reaction." (PMID 19912621, 2009). "It was proposed that HINT1-KO mice might even be affected by schizophrenia-like behaviors." (PMID 36873433, 2023). "Reviewing the available literature on HINT1, we found that HINT1 is highly related to many neuropsychiatric diseases including schizophrenia, mood disorder, drug addiction, and so on, and HINT1 may participate in neuropsychiatric diseases as a potential neuroplastic mediator." (PMID 29214080, 2017). "In humans, the HINT1 and σ1R genes have been implicated in schizophrenia, and mice lacking the HINT1 protein show an altered dopamine transmission that could mediate their tendency to drug abuse." (PMID 26461475, 2015). "The LIMMA analysis first detected a number of down-regulated genes in individuals with EDs that are known to be suppressed in schizophrenia or major depressive disorder, such as SST, NPY, SLC32A1, HINT1, and RELN." (PMID 29958387, 2018). "In this review we will discuss the possible relevance of the HINT1/σ1R tandem and its use by endocannabinoids to diminish NMDAR activity and their implications in psychosis/schizophrenia, as well as in NMDAR-mediated convulsive episodes." (PMID 27323834, 2016). "Among the candidates that may regulate in humans HINT1/NR1 C1 levels, the serotonin and endocannabinoid systems are important regulators of mood and emotions and are notable for being consistently related to both schizophrenia and depression." (PMID 29249810, 2017). "In the central nervous system, the levels of HINT1 were elevated in individuals diagnosed with major depressive disorder (MDD) without psychosis and reduced in individuals with schizophrenia." (PMID 39062900, 2024).
neuromyotonia (14 papers, 2016 to 2026). "An additional clinical hallmark of HINT1 deficiency is neuromyotonia, a peripheral nerve hyperexcitability characterized by spontaneous muscle activity at rest and delayed muscle relaxation following voluntary contraction." (PMID 41549766, 2026). "A homozygous missense variant in the Histidine triad nucleotide-binding protein 1 (HINT1) gene, linked to axonal neuropathy with neuromyotonia." (PMID 41509941, 2025). "To date, neuromyotonia in the context of an inherited axonal neuropathy has been linked to autosomal recessive mutations in the histidine triad nucleotide binding protein 1 (HINT1) gene." (PMID 40009145, 2025). "Loss of function mutations in HINT1 are associated in humans with autosomal recessive axonal neuropathy with neuromyotonia (ARAN-NM), probably due to the involvement of the gene product in neuronal signaling pathways." (PMID 39596683, 2024). "Biallelic loss-of-function alterations in the histidine triad nucleotide-binding protein 1 (HINT1) cause neuromyotonia and axonal neuropathy (NMAN [OMIM#137200])." (PMID 36242072, 2022). "Recessive loss-of-function variations in HINT1 cause a peculiar subtype of Charcot-Marie-Tooth disease: neuromyotonia and axonal neuropathy (NMAN; OMIM[#137200])." (PMID 36242072, 2022). "Loss-of-function alterations in the histidine triad nucleotide-binding protein 1 (HINT1) are associated with autosomal recessive axonal neuropathy with neuromyotonia (NMAN [MIM: 137200])." (PMID 33663550, 2021). "Autosomal recessive axonal neuropathy with neuromyotonia has been linked to loss of functional HINT1." (PMID 33663550, 2021). "HINT1 is a zinc- and CaM-regulated SUMO protease, and a series of HINT1 mutants have been reported to cause human autosomal recessive axonal neuropathy with neuromyotonia." (PMID 33020464, 2020). "Recently, interest in this protein has increased considerably because an initial report described a series of human HINT1 mutants as the cause of the devastating condition autosomal recessive axonal neuropathy with neuromyotonia (ARAN-NM)." (PMID 31088288, 2019). "Recently, a series of HINT1 mutants have been reported to cause human autosomal recessive axonal neuropathy with neuromyotonia (ARAN-NM)." (PMID 31088288, 2019). "In this context, the mutation of the HINT1 (histidine triad nucleotide-binding protein 1) gene in chromosome 5 is responsible for so-called autosomal recessive axonal neuropathy associated with neuromyotonia (ARAN-NM)." (PMID 38391750, 2024). "Changes in HINT1 gene are associated with autosomal recessive axonal neuropathy with neuromyotonia." (PMID 36873433, 2023). "Loss-of-function changes in the histidine triad nucleotide-binding protein 1 (HINT1) are associated with autosomal recessive axonal neuropathy with neuromyotonia (NMAN [MIM: 137200]), the symptoms of which are similar to those of Charcot-Marie-Tooth (CMT) disease." (PMID 36873433, 2023). "HINT1 mutations cause an autosomal recessive axonal neuropathy with neuromyotonia." (PMID 35501818, 2022). "HINT1 mutations may account for 11% of all inherited neuropathies with autosomal recessive inheritance and for 80% of individuals with axonal neuropathy having the clinical hallmark of neuromyotonia." (PMID 35501818, 2022). "A different amino acid substitution for Glycine (Gly, G) at position 93 of the HINT1 protein occurred in a patient with autosomal recessive axonal neuropathy with neuromyotonia." (PMID 35501818, 2022). "Even so, by using knockout mice, Seburn and colleagues demonstrated that HINT1 knockout mice may be useful for studying the biochemical activities of HINT1, but these mice do not provide a disease model or a means for investigating the basis of HINT1-associated neuropathy and neuromyotonia." (PMID 29214080, 2017).
neuromyotonia (continued). "Genetic testing revealed an autosomal dominant MPZ c.103G > A mutation, categorized in the Charcot-Marie-Tooth (CMT) 2 type, which, to our knowledge, are the first reported cases of hereditary neuropathy with neuromyotonia, not related to a mutation in HINT1." (PMID 40009145, 2025). "Finally, neuromyotonia on electromyography, a diagnostic hallmark of HINT1 neuropathy, was not present in any of our patients with DNAJB2 variants but in two patients with HINT1 variants, as expected." (PMID 41549766, 2026). "Thus, HINT1 dysfunction may contribute to different types of cancer and to axonal neuropathies with neuromyotonia." (PMID 31088288, 2019). "In the present study, we reported the first case of ocular MG, whose diagnosis was challenged by the coexistence of HINT1-related hereditary axonal neuropathy without clinical or electrophysiological features of neuromyotonia." (PMID 35501818, 2022). "This is a first case report of coexistence of myasthenia gravis (MG) and HINT1-related motor axonal neuropathy without neuromyotonia." (PMID 35501818, 2022).